ENSG00000236543 (novel beta-lactoglobulin-like protein)
Synonyms: LOC102723971
Gene: Protein-coding gene on chromosome 9 (135,604,345 to 135,619,893, forward strand). Ensembl gene ENSG00000236543.
Gene Ontology:
Molecular function: small molecule binding
Homologues: Orthologues: rat Lcn15l1 (68% identical), mouse Gm13539 (62% identical).